KIF11 (kinesin family member 11)
Diseases named in the same sentence as KIF11 in open-access papers (continued):
Sharing a sentence is not in itself a finding about the gene and the disease.
cancer (continued). "The KIF11 gene product, the kinesin Eg5, is the target of monastrol, a potent inhibitor of mitosis and a potential cancer therapeutic." (PMID 23840313, 2013). "While KIF11 inhibitors are under clinical development as mitotic blockers, our data reveal a new function for KIF11 in controlling lysosomal stability and introduce six other molecular motors as putative cancer drug targets." (PMID 23071517, 2012). "This should especially be tested for the already available KIF11 inhibitors, which have only modest anti-cancer effects as single agents." (PMID 23071517, 2012). "Of the identified kinesins, KIF11, also called kinesin spindle protein or Eg5, has been studied most extensively, especially in the context of cancer." (PMID 23071517, 2012). "Interestingly, patients showing both high KIF11 and low KIF14 expression were associated with the worst prognosis for this type of cancer." (PMID 41009541, 2025). "KIF11 inhibitors have been developed to interfere with the binding of KIF11 to microtubules or its ATPase activity and induce mitotic arrest and apoptosis in cancer cells." (PMID 41439111, 2025). "Future research could explore the correlation between three kinesin genes (KIF4A, KIF20A, and KIF11) and cancer stem cells, potentially leading to new discovery.However, there were a few limitations in this study." (PMID 41462522, 2025). "Considering the results shown, it is suggested that KIF11 may act as an oncogene throughout cancer progression." (PMID 40075652, 2025). "Therefore, further explorations of the pain modulation network regulated by KIF11 will help to guide the development of cancer treatments." (PMID 38672404, 2024). "KIF11 was found to be highly expressed in various types of malignant tumors, including LUAD." (PMID 39113697, 2024). "Then, we elucidate the mechanism of KIF11 to promote various hallmarks of cancers." (PMID 38672404, 2024). "Thus, studies on the KIF11 in signaling pathway regulation in cancer will continue to shed light on its involvement." (PMID 38672404, 2024). "Furthermore, we also studied mRNA expression based on cancer stage which showed overexpression of KIF11/15/23/18B/20A/2C/4A/C1 in tumor tissues." (PMID 37330525, 2023). "Recent studies have revealed that KIF11 plays an important role in cancer." (PMID 36742345, 2022). "Thus, the role of KIF11 in immune and molecular subtypes among human cancers was investigated via the TISIDB database." (PMID 36742345, 2022). "We thus identify a translationally actionable approach to overcoming Kif11 inhibitor resistance that may work to block STAT3-driven resistance against other anti-cancer therapies as well." (PMID 35732128, 2022). "All these results indicated that KIF11 expression was strongly related to genomic heterogeneity and genetic alternation of KIF11 indeed occurred in many cancers and might play essential roles in cancer onset and progression." (PMID 36742345, 2022). "In contrast, KIF11 was high expressed in almost all cancer cell lines." (PMID 36742345, 2022). "We analyzed KIF11 expression in pan-cancer, normal tissues, and various cell lines and evaluated the prognostic value and biomarker relevance of KIF11 in different human cancers." (PMID 36742345, 2022). "In conclusion, our study evaluated the prognostic and immunological value of KIF11 in pan-cancer." (PMID 36742345, 2022). "Taken together, our study revealed that KIF11 might serve as a potential pan-cancer biomarker for cancer detection, prognosis, therapy design, and follow up." (PMID 36742345, 2022). "Finally, the 5 RNAs, including CCNA2, MKI67, KIF11, miR-30a-5p, and VPS9D1-AS1, were further identified as candidate crucial RNAs associated with cancer." (PMID 35186743, 2022).
cancer (continued). "Furthermore, the activated KSP-coding gene KIF11 was detected in relapsed neuroblastoma oncogenic signaling pathways and many other cancer conditions." (PMID 35251692, 2022). "Additionally, we investigated the mRNA expression level of KIF11 across different normal tissues and cancer cell lines via the HPA database." (PMID 36742345, 2022). "On the contrary, KIF11 expressed at high level in cancer cell lines generally." (PMID 36742345, 2022). "In addition, we explored the relationships between KIF11 and tumor stemness, genomic heterogeneity, drug sensitivity, and therapy response in human cancers." (PMID 36742345, 2022). "In present study, we comprehensively interrogated the role of KIF11 in tumor progression, tumor stemness, genomic heterogeneity, tumor immune infiltration, immune evasion, therapy response, and prognosis of cohorts from various cancer types." (PMID 36742345, 2022). "In this study, we comprehensively interrogated the role of KIF11 in human cancers." (PMID 36742345, 2022). "They identified KIF11 inhibitor (originally indicated for several types of cancers), GSK3B inhibitor (originally indicated for several types of cancers), and AP-1 inhibitor (originally indicated for RA) as potential candidates for a repurposed treatment of T2D." (PMID 33691789, 2021). "Previous studies have discovered over-expression of KIF11 in a variety of cancers and suggested poor survival, while another study found that chromosome instability caused by KIF11 silencing or inhibition may contribute to the development of cancers." (PMID 34257537, 2021). "KIF11 is a key component of the bipolar spindle and is highly expressed in several cancer types." (PMID 33995648, 2021). "KIF11 inhibitors have been developed as chemotherapeutic agents to treat cancer." (PMID 32219041, 2020). "Several inhibitors of KIF11 such as Monastrol, Ispinesib, and Dimethylenastron have been developed and are in clinically used to inhibit cell proliferation and induce apoptosis to treat numerous cancers." (PMID 31681566, 2019). "This makes KIF11/Eg5, a human kinesin-5 ortholog, an attractive target for cancer chemotherapeutics, and several chemicals that interfere with its activity (kinesin-5 inhibitors or K5Is), and hopefully would impede proliferation of tumor cells, have been developed." (PMID 30557316, 2018). "Studies have demonstrated that inhibition of KIF11 could induce apoptosis and overcome drug resistance in various cancer cells." (PMID 29190901, 2017). "KIF11/Eg5 plays an important role in normal and cancer cell migration." (PMID 24327603, 2013). "Similarly to KIF11 siRNA, the KIF11 inhibitor monastrol induced lysosomal membrane permeabilization and sensitized several cancer cell lines to siramesine." (PMID 23071517, 2012). "However, the results showed that KIF11 silencing could rescue CVB-D-mediated cancer growth inhibition, though they both inhibited the NF-ΚB/JNK pathway, making this conclusion debatable." (PMID 38672404, 2024). "In addition, KIF11 expression was correlated with therapeutic response in clinical cancer cohorts." (PMID 36742345, 2022). "KIF11 may serve as a potential prognostic and immunological pan-cancer biomarker." (PMID 36742345, 2022). "Since KIF11 expression was significantly correlated with immune infiltration, we next explored whether KIF11 expression affected the prognosis of patients because of immune infiltration based on the expression level of KIF11 in various human cancers in related immune cell subgroups." (PMID 36742345, 2022). "Since KIF11 expression was significantly correlated with immune infiltration, whether KIF11 expression affects the prognosis of patients because of immune infiltration was analyzed based on the expression level of KIF11 in various human cancers in related immune cell subgroups." (PMID 36742345, 2022).
cancer (continued). "However, the function of KIF11 in tumorigenesis and tumor progression remains largely unknown from the perspective across multiple cancers." (PMID 36742345, 2022). "Moreover, an inhibitor of aurora A kinase could promote mono-astral spindle formation and mitotic catastrophe caused by KIF11 inhibitor, leading to apoptosis and tackling the potential resistance of the KIF11 inhibitor in cancer cells." (PMID 33995648, 2021). "Then, we investigated whether KIF11 modulated cancer cell proliferation in HCC cells." (PMID 33490265, 2021). "KIF11 is an evolutionarily conserved microtubule motor protein that functions in centrosome and chromosome dynamics in mitosis, KIF11 silencing induced increases in nuclear areas, micronucleus formation, DNA content and chromosome numbers that may contribute to the pathogenesis of cancer." (PMID 32886110, 2020). "Since CDK1, CHEK1, KIF11, PLK1 and TTK was significantly elevated with cancer progression in LUAD and exhibited excellent binding performance with 6-MDS, they were chosen for further validation." (PMID 38783288, 2024). "KIF11 and AURKA are overexpressed in many different cancer types, indicating the importance of this mitotic machinery to facilitate aggressive tumor growth." (PMID 37894278, 2023). "The results showed that CCNA2, CDK1, KIF11, MKI67, and PLK1 were significantly and positively correlated with CEP55 in pan-cancer." (PMID 37887301, 2023). "The correlation heatmap showed the top five genes (CCNA2, CKAP2L, KIF11, MKI67 and PLK1) that were positively and significantly related to RRM2 in almost all TCGA cancers." (PMID 35740608, 2022). "Our study found that KIF11 correlated negatively with immune, stromal, and ESTIMATE scores of the TME in most human cancer types but correlated positively with immune, stromal, and ESTIMATE scores of the TME in KIPAN, KIRC, and THCA." (PMID 36742345, 2022). "For single immune checkpoint gene, the immune stimulator HMGB1 correlated positively with KIF11 in all human cancer types, and TNFSF4, BTN3A1, BTN3A2, and ENTPD1 correlated positively with KIF11 in most human cancer types." (PMID 36742345, 2022). "We further investigated the dependency of the KIF11 gene in various cancer types using the CERES dependency score, which was based on CRISPR screening data of hundreds of cancer cell lines from publicly available datasets." (PMID 36123339, 2022). "The immune inhibitor CD276 and VEGFA correlated positively with KIF11 in most human cancer types, but VEGFB correlated negatively with KIF11 in most human cancer types." (PMID 36742345, 2022). "Cox regression analyses of the correlations between KIF11 and OS, DFI, DSS, and PFI in different cancers were displayed in forest chart." (PMID 36742345, 2022). "First, although we investigated the protein level of KIF11 via the IHC data of HPA database, the IHC results of some cancer types are missing in the HPA database." (PMID 36742345, 2022). "We found that KIF11 and KIF14 expression, at both the protein and mRNA level, was markedly altered in cancer tissues compared to respective controls, which was reflected in the clinical outcome of CRC patients." (PMID 34575892, 2021). "Here, we exploited a novel pyrrole subclass payload that potently inhibits the kinesin spindle protein (KSP/KIF11/Eg5) in biochemical and cellular assays to develop an ADC to target IL3RA on cancer cells." (PMID 33233768, 2020). "Thus, miR‐30a may be involved in the regulation of KIF11 in cancer progression." (PMID 32346924, 2020).
cancer (continued). "Fourteen genes that are essential to prevent EDR in cancer cells also are essential to prevent aneuploidy in mice [AURKA, BUB1B, BUB3, KIF11, MAD2L1, TPX2, TTK, SGOL1." (PMID 27144335, 2016). "THS–PAMAM protects siRNA from degradation by RNase A and traffics KIF11 and GAPDH siRNA into U87 cancer cells." (PMID 27840795, 2016). "Understanding the mechanisms by which KIF11 and KIF14 influence cancer progression could inform the development of targeted therapies aimed at modulating their expression or function, potentially improving prognoses for patients with various malignancies." (PMID 40075652, 2025). "Furthermore, KIF11 plays a role in the PI3K/AKT, MAPK/ERK, and NF-κB/JNK signaling pathways, contributing to cancer cell invasion and promoting the epithelial–mesenchymal transition (EMT) process." (PMID 40075652, 2025). "Emerging recent evidence suggests that targeting CDK1 and KIF11 could be a promising therapeutic strategy for CRC and other cancers." (PMID 40457491, 2025). "Some previous reports from other authors have found that high KIF11 expression was significantly correlated with aggressive clinical characteristics of cancer, but we did not observe any significant relationships." (PMID 40075652, 2025). "In addition, the expression level of CDK1, CHEK1, KIF11, PLK1 and TTK was significantly elevated with cancer progression in LUAD." (PMID 38783288, 2024). "Besides, the expression level of CDK1, CCNA2, CHEK1, KIF11, PLK1 and TTK was significantly elevated with cancer progression in LUAD." (PMID 38783288, 2024). "KIF11 could be a target in TNBC, where its pharmacological inhibition revealed a slowdown in tumorigenesis and cancer progression in in vivo xenograft models." (PMID 38939361, 2024). "Thus, the combination treatment strategy for cancers, especial HCC, by inhibiting NEAT1 and KIF11, has great potential for clinical application." (PMID 37752791, 2023). "Hence, dual inhibition of KIF11 and the KIF15/TPX2 axis is essential to disrupt the mitotic activity of cancer cells." (PMID 37894278, 2023). "KIF11 silencing induced chromosome instability (CIN), which might contribute to cancer development and progression." (PMID 35421138, 2022). "These hallmarks were mostly correlated with programmed cell death signaling pathways, suggesting regulation of the cell cycle to promote apoptosis of cancer cells by changing the gene expressions such as knockdown of KIF11 and SNRPG,which is conducive to cancer control for patients of C2 subtype." (PMID 35586564, 2022). "KIF11 labeling was cytoplasmic with occasional concurrent staining of the membrane (n = 4/86; 4.65%) in cancer cells and fully restricted to the cytoplasm in nontumor cells." (PMID 34575892, 2021). "KIF11, KIF15, and KIF23 are overexpressed in several cancer types." (PMID 32642733, 2020). "Although we identified the requirement of KIF11 for the transport of β-actin mRNP in fibroblasts and carcinoma cells, KIF5A was not shown to be involved in this cellular process." (PMID 25588836, 2015). "In this study, we identified KIF11, KIF20A, KIF21, KIF25, MYO1G, MYH1 and TPM2 as proteins whose depletion causes growth inhibition and non-apoptotic cell death in cancer cells." (PMID 23071517, 2012). "Interestingly, this pharmacological inhibition determined not only a downregulation of KIF11 expression, but also a downregulation of Aldehyde Dehydrogenase 1 family member A1 (ALDH1-A1): this is a marker of cancer stem cells (CSCs) and its high expression is correlated with poor overall survival." (PMID 38939361, 2024). "However, the prognostic, oncological, and immunological values of KIF11 have not been comprehensively explored in pan-cancer." (PMID 36742345, 2022). "KIF11 is reported highly expressed in proliferating compared with non-proliferating cancer cells." (PMID 29190901, 2017). "Thus, all siRNAs sensitized cancer cells to one or several lysosome-disrupting drugs with the strongest effects observed in cells lacking KIF11 or KIF21A." (PMID 23071517, 2012).
cancer (continued). "Additionally, the non-mitotic roles of KIF11 in neurons may give insights into the role of KIF11 inhibition in the elongation of axons and cancer pain regulation." (PMID 38672404, 2024). "However, the molecular mechanisms of KIF11 in cancers have not been systematically summarized." (PMID 38672404, 2024). "However, the oncological role of KIF11 has not been comprehensively explored in pan-cancer." (PMID 36742345, 2022). "However, although these inhibitors have demonstrated excellent efficacies in certain human cancer with no neurotoxicity, none have been used as a marketed anticancer agent; thus, further investigation is warranted to in the development of KIF11-based anticancer drugs." (PMID 33376723, 2020). "It is, therefore, not surprising that the aberrant expression of KIF11 or KIF14 disturbs centrosome separation, bipolar spindle assembly, chromosome segregation, and cytokinesis, which eventually can result in GIN and the development and/or progression of a broad spectrum of cancers." (PMID 34208606, 2021).